CD4 (CD4 molecule)
Diseases named in the same sentence as CD4 in open-access papers (continued):
Sharing a sentence is not in itself a finding about the gene and the disease.
tumor (continued). "Th1 type CD4+ cells most likely support a robust anti-tumor immune response, while CD4+ Treg cells are immunosuppressive." (PMID 37251920, 2023). "Although sitagliptin was still able to reduce tumor volume when anti-CD4/anti-CD8 was used to deplete T cells, the coexistence of T cells with eosinophils yielded the most optimal result, indicating a synergistic effect between T cells and eosinophils." (PMID 37587450, 2023). "As expected, human naïve CD4+ T cells induced Foxp3+ Tregs generation in the tumor microenvironment." (PMID 36814928, 2023). "The local buildup of kynurenine concentrations within the TME also triggers deleterious alterations in the metabolic properties of tumor infiltrating T cells and converts CD4 effector cells to Tregs." (PMID 37114134, 2023). "In the tumor microenvironment, T cells are highly heterogeneous, consisting of many subtypes of CD4+ and CD8+ T cells." (PMID 36969495, 2023). "Accumulation of somatic mutations during oncogenesis has been shown to result in the presentation of neoantigens at the tumor cell surface, which can elicit tumor-specific CD4+ and CD8+ T cells with antitumor potential." (PMID 37371815, 2023). "On 43 GBM, they observed a low number of CD3+in larger tumor size, a low CD4+ in methylated MGMT and a low CD8+ related to methylation." (PMID 37584750, 2023). "Mechanistic studies revealed concordant rise in CD8+ and CD4 T cells and NK cells in the tumor microenvironment." (PMID 36411943, 2023). "We also found an association between high presence of tumor-budding and increased CD4+ T-cell infiltration in the invading front of the tumor." (PMID 36900270, 2023). "CASP8 expression was negatively correlated with dendritic cells and uncorrelated with tumor purity, CD4+ T cells, and neutrophils." (PMID 36533709, 2023). "Since little is known about the expression of immune checkpoint receptors on tissue-resident innate lymphocytes, we assessed their expression on trNK cells, ILCs, CD8+ TRM, and CD4+ TRM cells in the distinct tumor locations." (PMID 37448786, 2023). "Ectonucleotidases (CD39 and CD73) hydrolyze exATP to ADO and increased ADO inhibits the anti-tumor function of innate immune cells and effector T cells (Teff, CD4+ and CD8+), and monocyte differentiation into associated tumor macrophages 2s." (PMID 36741002, 2023). "We used a pair of OX40 antibodies with approximately four-fold difference in their ADCC activity, and found that treatment with ADCC-enhanced BAT6026 resulted in significantly fewer CD4+ T cells and Treg cells in mice tumor than with BAT6026-wt." (PMID 37576888, 2023). "Specifically, we observed higher expression levels of major anti-tumor immune cells such as CD8+ T cells, CD4+ T cells, and macrophages in the high-risk group by TIMER analysis." (PMID 37629096, 2023). "CD4+ T cells have been proven to inhibit tumor growth by inhibiting tumor blood vessel formation and maintenance." (PMID 37829505, 2023). "We then assessed STAT1 activity in tumor-bearing mice treated with CAR4 T cells or control CD4+ T cells (CTRL4)." (PMID 37248395, 2023). "As tumors have fewer candidate neoantigens compared with normal cells, this specially indicates the functional significance of CD4+ T cells for tumor treatment." (PMID 37508545, 2023). "The IHC results of our experiments revealed upregulated CD39 expression after cryoablation, as well as an increased number in the tumour microenvironment and a trend towards deeper infiltration of CD4+CD39+ and CD8+CD39+ T cells." (PMID 37157934, 2023). "As tumours progressed, the frequency of CD4+ FoxP3-T-bet- TILs decreased but still accounted for 55% of total CD4+ TILs in D21 tumours, while TH1 (FoxP3-T-bet+) and TREG (FoxP3+T-bet-) subsets remained relatively stable." (PMID 37153625, 2023).
tumor (continued). "It is traditionally believed that CD8+ T cells are mainly involved in anti-tumor immunity, but researchers have come to realize the importance of CD4+ T cells." (PMID 36960067, 2023). "The lymphocytes around the tumor were CD4/8 positive T cells, which play an important role in cancer cytotoxicity." (PMID 37878146, 2023). "The OX40+ Treg cells can arrive from tertiary lymphoid structures or differentiate independently from CD4+FOXP3- T helpers inside the tumor." (PMID 38136307, 2023). "To this aim, we analyzed a panel of tumor-infiltrating immune cells, including CD4+ T lymphocytes, CD8+ CTL, NK cells, and macrophages, by flow cytometry." (PMID 36959575, 2023). "In contrast to CD8+ T cells, metformin inhibited tumor growth, decreased IL-22 production and de novo generation of Th1- and Th17 cells from naïve CD4+ cells in a mouse hepatocellular carcinoma model." (PMID 36614197, 2023). "They showed that bacteria-positive areas of tumor tissue had lower densities of CD4+ and CD8+ T cells, as well as increased CD11b+ and CD66b+ myeloid cells, compared with bacteria-negative areas." (PMID 36960042, 2023). "CD4 with co-expression of TIM-3 was more abundant in the tumor compared to interface (p = 0.0137), just as was CD4 with PD-1 and TIM-3 co-expression (p = 0.027)." (PMID 36980192, 2023). "Since apCAFs have been reported to present antigens to CD4+ T cells and are therefore believed to be involved in the anti-tumor process, more evidence is anticipated to fully unravel its anti-tumor role." (PMID 37784082, 2023). "CD3 T (P = 0.039), FoxP3 T (P = 0.038), and CD3+CD4+ T (P = 0) cells were more abundant in the tumor rim of HACC than in HER2-negative CRC samples." (PMID 37151285, 2023). "PTM-specific CD4 T-cell responses have shown tumour therapy in murine models and highlight the importance of CD4 T cells as well as CD8 T cells in reversing the immunosuppressive tumour microenvironment." (PMID 38567060, 2023). "Spatial parameter analysis showed that high colocalization of tumor cells and immune cells (CD3+, CD4+, or CD8+) was significantly associated with patient survival." (PMID 37090736, 2023). "Upon DSP, the stroma featured higher expression of immune cells markers (CD45, CD3, CD8, CD4 and CD11c) compared with tumour, consistent with parallel messenger RNA analysis." (PMID 37835491, 2023). "CD4+ helper T cells stimulate an anti-tumor response by activating CD8+ cytotoxic T cells and promoting B cell proliferation and differentiation." (PMID 37601668, 2023). "Numerous studies have shown that antitumor vaccines based on synthetic peptides are safe and can induce both CD8+ and CD4+ tumor-specific T cell responses." (PMID 38260723, 2023). "It is a chemokine that interacts with T cells by binding CXCR3, inducing the recruitment of CD8+ lymphocytes to the tumor microenvironment and inducing the differentiation of inflammatory T helper type 1 (Th1) and Th17 CD4 cells." (PMID 36900006, 2023). "In line with the observation of reduced inflammatory response, LMS cases in P1 displayed an “immune cold” phenotype with less CD3+ and CD4+ tumour infiltrating lymphocytes (TILs) compared to the other two clusters (p = 0.008)." (PMID 37386008, 2023). "Neutralizing TIGIT with anti-TIGIT antibodies has resulted in the partial recoveries of IFNγ and IL-17 expression by CD4+ T cells, suggesting it is a considerable marker to reactivate the immune system against tumor development." (PMID 37046842, 2023). "Here, we detected three adaptive immune indicators in the tumour region, including CD4+ T, CD8+ T and Tregs cells." (PMID 37471521, 2023). "Flow cytometry results showed that the combination of anti-PD-L1 with ArgNP promoted infiltration of CD8+ Teff cells and elevated the ratio of CD8+/CD4+ T cells in tumor tissues." (PMID 37901179, 2023). "The expression of IGF2BP3 was significantly positively correlated with tumor purity and CD4+T cells." (PMID 36793593, 2023).
tumor (continued). "There is also evidence that anti-Gal-9 antibodies promote the expansion of cytotoxic CD8+ cells in a mamary tumor mouse model, reducing a population of tumor-enabling Treg cells (CD4+, Foxp3+, CD25+)." (PMID 38022609, 2023). "The induction of chemokines such as CXCL-9 or CXCL-10 by IFN-λ recruits CD4+ T cells into the tumor environment, and antitumor responses of CD8+ T cells and natural killer (NK) cells are enhanced in various types of tumors." (PMID 37374093, 2023). "Changes in the number of CD4+ T cells are vital in creating robust hosts against tumours, especially for lymph node metastasis." (PMID 37270478, 2023). "It is considered that CD4+ T cells contribute to anti-viral and anti-tumour immune response by producing cytokines that lead to activation of CD8+ T cells." (PMID 38129531, 2023). "CD4+ T cells from peripheral blood of 5 healthy controls, peripheral blood and tumor tissues of 5 OC patients were extracted." (PMID 37950246, 2023). "A recent mouse study pinpointed that CD40 activation on cDC1 is essential for priming a CD4+ T-cell response to cell-associated antigen and help for CTL-based tumor rejection." (PMID 36639382, 2023). "Here we summarize preclinical and clinical data indicating killing of MHC class II-positive tumor cells by CD4+ CTL and highlighting the therapeutic potential of this T cell subset." (PMID 37965314, 2023). "It's worth noting that EVs derived from IL-2-stimulated CD4 T cells induce a more robust anti-tumor response in CD8 T cells when compared to those from unstimulated CD4 T cells." (PMID 38087360, 2023). "Among them, the activated CD8 + T cells, type I CD4 + helper T cells (Th1 cells) and γδ T cells in the low TRscore group interacted with tumor-killing immune cells." (PMID 37208604, 2023). "Immunohistochemistry (IHC) staining was performed using (i) PD-L1 antibodies to detect PD-L1 expressions; (ii) CD8 and CD4 to detect Tumor Infiltrating Lymphocytes (TILs); and (iii) CD44, LGR5, and ALDH2 to detect stem cell markers." (PMID 36604635, 2023). "Targeting the elevated expression of LAG-3 on CD8+ and CD4+ T cells in the blood and bone marrow of patients with multiple myeloma will help enhance the proliferative and anti-tumor capacity of T cells." (PMID 37055849, 2023). "We found that macrophages and memory-activated CD4+ T cells were significantly elevated in tumor from the nsPEF group (p < 0.01 and p < 0.05, respectively)." (PMID 37046739, 2023). "Although CD4+ T cells were also detected, the ratio of this subset was not influenced significantly in the spleen or peripheral blood of H22 tumor‐bearing mice." (PMID 36043445, 2023). "Treg depletion had a stronger contribution to tumor regression than the requirement of CD4+ T-cell help." (PMID 37833255, 2023). "Our collective data indicate that contact with activated CD4+ T-cells programs cDC1 to boost all molecular programs that are important for optimal anti-tumor immunity." (PMID 36639382, 2023). "The results showed that photoablation inhibits primary tumors and leads to an increase in CD8+ and CD4+ T cells at the tumor site, which can also enhance the presence of mature DCs in the tumor." (PMID 37238966, 2023). "Using ovalbumin as a second tumour antigen model, we recapitulated the different in vivo expansion dynamics of adoptively transferred ovalbumin-specific OT-II TCRtg CD4+ T cells and OT-I TCRtg CD8+ T cells." (PMID 37316667, 2023). "For example, in a preclinical study, tumor-specific CD4 and CD8 T cells were found to metabolically reprogram phosphoenolpyruvate carboxylation kinase 1 (PCK1) by increasing the glycolytic metabolite phosphoenolpyruvate (PEP) to enhance the antitumor response." (PMID 38026944, 2023). "We performed an in vitro CTL killing assay using CD4 T cells with either high PD-1 (from PBS-treated tumor-bearing mice) or low PD-1 (from methionine-treated tumor-bearing mice) expression levels." (PMID 37147330, 2023).
tumor (continued). "Anti‐tumor systemic activities were mediated mainly by circulating NK cells, with a minor contribution by CD4 and CD8 T cells." (PMID 37366231, 2023). "Furthermore, our results may allow us to test whether engineering the IFN-γR/JAK1/STAT1 signaling pathway in APCs could be of value in achieving a more efficient presentation of endogenous tumor–associated peptides to CD4+ T cells and potentially enhancing tumor responses." (PMID 36445781, 2023). "T cell stimulation through GITR attenuates Treg-mediated suppression or enhances tumour-killing by CD4+ and CD8+ effector T cells, including those secreting IFN-γ, or both." (PMID 36980527, 2023). "CD8+, CD4+ T cells, and NK cells are known to mediate tumor immunosurveillance in the lungs against invading tumor cells." (PMID 36839766, 2023). "CAA-derived CXCL8 remodeled the tumor immune microenvironment not only by suppressing CD4+ T and CD8+ T immune cell infiltration but also by upregulating CD274 expression in TNBC." (PMID 37898619, 2023). "Functional annotation and enrichment analyses revealed an upregulation of gene sets associated with anti-tumor immunity, especially within subsets of CD8+ T-cells and to a lesser extent CD4+ T-cells." (PMID 37077913, 2023). "Preclinical data on GITR-agonist monoclonal antibodies demonstrated in vitro and in vivo antitumor activity which enhances the CD8+ and CD4+ effector T cells and decreases tumour-infiltrating Tregs." (PMID 37483633, 2023). "Studies in the field of tumor microenvironment (TME) have shown that tumor cells exploit the immunosuppressive capacity of CD4+Treg in TME to evade immune surveillance and promote tumor progression." (PMID 38250084, 2023). "CD4+ T cells can promote tumor regression through various mechanisms, including cytokine secretion (IL-2), enhancing tumor-specific CD8+ T-cell function, or directly eliminating cancer cells." (PMID 37638022, 2023). "High SLC1A5 expression is associated with poor overall survival, as well as increased numbers of tumor-infiltrating B cells, CD4+ T and CD8+ T cells, macrophages, neutrophils and dendritic cells." (PMID 36902506, 2023). "There is decreased tumor growth by up-regulating pro-inflammatory cytokines and inducing the activation and migration of CD4+ and CD8+ T cells." (PMID 37443821, 2023). "Strong correlation was found between the increase of tumor infiltrating lymphocytes (such as CD4+and CD8+T cells) and the normalization of blood vessels imposed by VEGF pathway inhibitors." (PMID 37007075, 2023). "Since NF-κB activity is most commonly associated with resistance to therapy, we searched for drivers of therapeutic sensitivity and found an increased number of tumor-infiltrating CD4+ cells." (PMID 37523561, 2023). "The tumor microenvironment showed the presence of CD4+ T cells (86%); CD8+ T cells (27%); CD20+ B (67%); CD15+ cells (86%); and CD163+ M2 macrophages (67%), while CD56+ NK cells were absent." (PMID 37509688, 2023). "We also detected a higher level of IL-17 in the medium from the co-culture including Tcf7-null CD4+ T cells and tumor cells, as measured by ELISA." (PMID 36239683, 2023). "This inhibition was further reflected by Tregs’ loss of function followed by the infiltration of CD4+ and CD8+ T cells to the site of the tumor." (PMID 36672682, 2023). "Unsurprisingly, tumor-bearing greatly increased the percentages of neutrophils, monocytes, and dendritic cells but moderately decreased those of CD4+ T cells, CD4 + CD25+ T cells, CD8+ T cells, B cells, and NK cells in the spleen." (PMID 38067390, 2023). "These interactions result in the generation and expansion of activated tumor-specific CD4 + and CD8 + T cell populations, which can then migrate to the tumor site and destroy tumor cells." (PMID 37420174, 2023). "Activated memory CD4+ T cells induce a robust anti-tumor response in the early stage of tumor progression." (PMID 36675039, 2023).
tumor (continued). "Cox multivariate analysis showed a high risk of death for non-operated patients [hazard ratio (HR), 3.42 (1.15–10.16)] with low tumor mesothelin levels [HR, 2.58 (1.09–6.10)] and high PD-L1 and low infiltration of T cells CD4+ [HR, 3.81 (1.58–9.18)]." (PMID 37901248, 2023). "In groups A5, A6, A7, and A8, genes such as CXCL13, HSPA1A, CREM, CCL4, and FOS were highly expressed in CD8+ or CD4+ T cells in tumor tissues." (PMID 37762493, 2023). "To further assess the role of T‐cell populations in preventing tumorigenesis, we conducted additional experiments to investigate the effects of RBC‐Nanovaccines on tumor growth in mice depleted of CD8+ or CD4+ T cells." (PMID 37552209, 2023). "Intense lymphocytic infiltration predicts longer survival, and high density of T lymphocytes (CD4+ and CD8+) in tumor stroma was associated with better outcome." (PMID 37002211, 2023). "The 4T1 tumor model displayed expansion and activation of CD4+ T, CD8+ T, and NK cells upon combination treatment with sICAM‐1 and anti‐PD‐1, compared to anti‐PD‐1 therapy alone." (PMID 37097643, 2023). "We found that arachidonic acid activated NLRP3 inflammasome in MDSCs through FATP2 during fatty liver graft injury, which led to more IL-17 secretion of CD4+ T cells and promoted tumour recurrence post transplantation." (PMID 37916155, 2023). "When combining the three groups, there were significantly more regulatory T cells to CD4, more myeloid cells and more B cells in the tumor tissue of the central tumor slide compared to invasive front." (PMID 37587309, 2023). "EMP3 knockout combined with anti-PD-1 therapy resulted in tumor growth inhibition by promoting T cell (CD4+ and CD8+) infiltration mediated by the CXCR3 axes." (PMID 38104126, 2023). "Their results revealed that the TME of these tumors is characterized by a low infiltration of tumor-specific CD8+ T cells, marked by CD39+, which is associated with a high infiltration of hyper-activated CD4+ regulatory T cells (Tregs)." (PMID 37190304, 2023). "The occurrence and development of COAD is affected by the tumor microenvironment, and T cells, memory CD4 cells, M0 macrophages, and plasma cells are the most common tumor-infiltrating immune cells." (PMID 37626132, 2023). "Next our immune infiltration found that LRRC59 correlated with multiple tumor‐infiltrating immune cells, such as naive CD4 T cells, gamma delta T cells, NK cells, and Tregs." (PMID 37706625, 2023). "Clear cell and nccRCCs showed significant differences in the numbers of CD4 + TILs in the tumor center, both in the stroma (p = 0.02) and intratumorally (p = 0.03)." (PMID 36562826, 2023). "This triggers the activation of CD8+ CTLs and CD4+ helper T cells, which work synergistically to eliminate tumor cells." (PMID 37681891, 2023). "In PDAC, PD-1 is expressed on the majority of regulatory and CD4 T cells within the tumor-infiltrating lymphocytes, but there presence on CD8 T cells in contradictory as both high abundance and very low abundance has been described." (PMID 37938368, 2023). "While CD8+ cells exhibited a robust short-term effector function but became rapidly exhausted, CD4+ CAR-T cells persisted after tumor interaction and sustained their effector potency." (PMID 37443804, 2023). "FKN expression significantly enhanced immune infiltration of the tumor, mainly with CD4 T and NK cells." (PMID 37366231, 2023). "CD4+ T cells are markers of helper T cells, which play an important role in anti-tumor immunity; CD8+ T cells are divided into cytotoxic T cells and suppressor T cells, whose cytotoxicity can damage vaginal epithelial cells." (PMID 38223622, 2023). "Immunosuppressive cytokines, such as IL-6 and IL-10, interfere with the antitumor effects of CD8+ and CD4+ T cells in the tumor microenvironment." (PMID 36639681, 2023). "The proportion of activated memory CD4+ T cells was marginally higher in tumor with high CRS signature compared to low CRS signature (2.29% vs. 1.26%, p = 0.075)." (PMID 36621808, 2023).